APOL1 (apolipoprotein L1)
Diseases named in the same sentence as APOL1 in open-access papers (continued):
Sharing a sentence is not in itself a finding about the gene and the disease.
COVID-19 (continued). "The inflammatory response to COVID-19 may act as a “second hit” for APOL1 variants that at baseline are at high risk for developing glomerulopathy." (PMID 40552181, 2025). "It is theorized that COVID-19 triggers an inflammatory cascade that may affect the APOL1 variant gene, causing glomerular impairment." (PMID 37024977, 2023). "More recent research has demonstrated that G1 and G2 variant alleles may increase the risk of COVID-19-associated collapsing glomerulopathy, including in the case above where genetic testing revealed homozygous APOL1 mutation (G1 allele)." (PMID 37485073, 2023). "Together, our results support the conclusion that COVID-19–induced cytokines are sufficient to drive COVAN-associated podocytopathy via JAK/STAT/APOL1 signaling and that JAK inhibitors could block this pathogenic process." (PMID 35472001, 2022). "We hypothesized that cytokines induced by COVID-19 trigger expression of pathogenic APOL1 via JAK/STAT signaling, resulting in podocyte loss and COVAN phenotype." (PMID 35472001, 2022). "In addition, the genotype of apolipoprotein L1 variant (APOL1) is another genetic risk factor for collapsing glomerulopathy in COVID-19 patients." (PMID 36142634, 2022). "This could also suggest that CG in COVID-19 is part of a second hit phenomenon in patients with APOL1 risk alleles." (PMID 33668833, 2021). "ACE polymorphisms and the high-risk apolipoprotein L1 (APOL1) genotype variants have been recently described as genetic modifiers associated with a higher proinflammatory state and podocyte damage in patients with coronavirus diseases (COVID-19)." (PMID 34406477, 2021). "Genetic factors may also be contributory, as the APOL1 high risk genotype was found in a case series of African-American patients with COVID-19 who developed collapsing glomerulopathy and the need for RRT." (PMID 34383798, 2021). "However, the susceptibility of black patients to COVID-19, including renal manifestation, suggests involvement of apolipoprotein L1 (APOL1) variants, which are more common in those of African descent, in this phenomenon." (PMID 33804075, 2021). "Acute tubular necrosis occurred almost invariably in the setting of severe forms of COVID-19, whereas patients with glomerular injury had various profiles of COVID-19 severity and collapsing glomerulopathy was only observed in patients harboring a combination of APOL1 risk variants." (PMID 34185186, 2021). "Interestingly, COVID-19 patients with risk allele genotypes for apolipoprotein L1 (APOL1) have been shown to exhibit a collapsing glomerulopathy phenotype." (PMID 34767537, 2021). "Although COVID-19 infection may serve as a second hit to the kidneys in black patients with variants of APOL1 gene resulting in COVID-19 related glomerulopathy and consequent worse outcomes, our study suggests otherwise." (PMID 34957809, 2021). "Although our results show that COVID-19–induced cytokines are sufficient to induce APOL1 expression and cause the loss of kidney micro-organoid podocytes, they do not exclude the possibility that SARS-CoV-2 may also directly infect kidney cells, as was recently reported." (PMID 35472001, 2022). "Thus, our study suggests that the collapsing glomerulopathy phenotype in COVID-19+ risk allele patients may be a consequence of APOL1 induction in podocytes following IFN-γ exposure, rather than direct infection by the virus." (PMID 34767537, 2021). "Podocytopathy and protein overload tubulopathy were observed in COVID-19 patients, with APOL1 genotypes potentially influencing severity." (PMID 41009556, 2025). "Kidney organoids can respond to inflammatory cues to produce changes in gene expression and cell death relevant to COVID-19 and APOL1-mediated kidney disease." (PMID 40964278, 2025). "Our recent investigation of the link between COVID-19, APOL1 HRG, and COVAN shows that COVID-19-induced cytokines synergistically drive APOL1 expression and cytotoxicity in human kidney cell models." (PMID 39291186, 2024).
COVID-19 (continued). "Together with previous knowledge that iatrogenic interferons cause collapsing glomerulopathy in patients with APOL1 HRG, these recent findings strongly suggest that cytokines induced by COVID-19 act as second-hit drivers of COVAN." (PMID 39291186, 2024). "It is believed that COVID-19 triggers a similar inflammatory response and this is why patients with the APOL1 genotype are more prone to developing COVAN." (PMID 37024977, 2023). "Our results verified that the major pathological feature of COVID-19 is ATI, which was associated with CG in patients with APOL1 high-risk gene variants." (PMID 36749641, 2023). "COVID-19–induced cytokines are sufficient to drive APOL1 expression in human induced pluripotent stem cell–derived kidney micro-organoids via the JAK/STAT pathway." (PMID 35472001, 2022). "Our major conclusions from the present study are that several COVID-19–induced cytokines, beyond IFNs, act synergistically via JAK/STAT signaling to drive pathogenic APOL1 expression, resulting in podocyte injury and loss, which are blocked by JAK inhibition." (PMID 35472001, 2022). "Recombinant COVID-19–induced cytokines synergistically upregulate APOL1 expression in primary human GECs and podocytes." (PMID 35472001, 2022). "Together, these results demonstrate that JAK/STAT signaling is the primary pathway that mediates COVID-19 cytokine–induced APOL1 expression." (PMID 35472001, 2022). "Plasma levels of APOL1 were higher in patients with severe sepsis and COVID-19 and correlated with markers of endothelial dysfunction." (PMID 35095882, 2021). "Our case highlights a similar case of COVID-19 in a 65-year-old AA descendant with biopsy-proven FSGS and genetically confirmed APOL-1 alleles." (PMID 34367703, 2021). "The APOL-1 gene, associated with the African American population, has been increasingly recognized as a risk factor for FSGS affected with COVID-19." (PMID 34367703, 2021). "APOL1 testing and kidney biopsy should be considered in black COVID-19 patients who have rapidly progressive kidney disease in the setting of nephrotic-range proteinuria." (PMID 34957809, 2021). "APOL1 genotyping in non-AA patients associated with COVID-19 was rarely performed, and ancestry was not always specified in the reviewed literature." (PMID 37229730, 2023). "FSGS associated with COVID-19 can occur rarely with low-risk APOL1 variants in non-AA and AA patients." (PMID 37229730, 2023). "Regardless of the mechanisms, the findings that there are cases of collapsing FSGS in AA and non-AA patients with COVID-19 and low risk APOL1 variants suggest that it would be misleading to assume that everyone with this disease has APOL1 high-risk variants." (PMID 37229730, 2023). "JAK/STAT signaling mediates COVID-19-cytokine–induced APOL1 expression." (PMID 35472001, 2022). "Second, because multiple COVID-19–induced cytokines redundantly activate the JAK/STAT pathway to induce APOL1 expression, a therapeutic strategy based on selective removal or inhibition of any 1 cytokine is unlikely to be effective in preventing or treating COVAN." (PMID 35472001, 2022). "APOL1 expression was abundant in glomeruli of patient 1, who underwent biopsy 10 months after COVID-19 diagnosis, and patient 6, who underwent biopsy 9 days after COVID-19 diagnosis." (PMID 35472001, 2022). "In fact, studies have confirmed the strong association of CG and non-collapsing podocytopathies with concurrent or recent COVID-19 in patients with APOL1 high-risk alleles." (PMID 35308512, 2022). "This suggests that the presence of APOL-1 may have a protective effect in African American COVID-19 patients with renal involvement and results in decreased mortality." (PMID 35950159, 2022). "On the basis of this background information, we hypothesized that the JAK1/2-STAT1/2/3 pathways are the primary mediators of the effects of COVID-19–induced cytokines in driving APOL1 expression." (PMID 35472001, 2022).
COVID-19 (continued). "We next investigated whether COVID-19–induced cytokines upregulate APOL1 expression via a common intracellular signaling pathway that could be exploited as a therapeutic target." (PMID 35472001, 2022). "There may be an association with APOL1 risk allele and COVID-19-related CG among Blacks which suggests that this group is more likely to develop APOL1-related kidney disease after exposure to COVID-19." (PMID 33668833, 2021). "Apolipoproteins APOA1, APOA2, APOL1, and APOM, which have been previously reported to be associated with macrophage and decreased in COVID-19 patients, were all downregulated in the CSF from the eight COVID-19 patients." (PMID 34956212, 2021). "It is possible that a pre-existing state of immune dysregulation (e.g., SLE, HIV, transplant immunity) may predispose or “prime” cytokine pathways to be triggered by COVID-19, resulting in cFSGS even in the absence of high-risk APOL1 mutations." (PMID 40552181, 2025). "Importantly, the findings also suggest that the synergy of COVID-19–induced cytokines may be more relevant for APOL1 regulation than the impact of an isolated cytokine alone." (PMID 35472001, 2022). "The strong epidemiologic association between high-risk APOL1 genotype and COVAN has led to the hypothesis that COVID-19–induced expression of APOL1 G1 or G2 in podocytes and glomerular endothelial cells (GECs) — the kidney cells affected in collapsing glomerulopathy — drives pathogenesis of COVAN." (PMID 35472001, 2022). "It is conceivable that the farther one is from the COVID-19–induced cytokine storm, the weaker the acute-phase reactants downstream of the cytokine receptor become, including phosphorylated STAT proteins and APOL1 mRNA." (PMID 35472001, 2022). "In addition to multiple socioeconomic and health risk factors associated with adverse outcomes in people of Black race in COVID-19, AKI-specific risk may in some part be attributable to the possession of high-risk APOL1 genotypes, which are present in people of West African ancestry." (PMID 34661677, 2022). "If COVID-19-induced cytokines trigger COVAN in individuals with APOL1 HRG, why did SARS-CoV-2 vaccine, which also increase systemic cytokines, not increase the incidence of glomerulopathy in individuals with APOL1 HRG?" (PMID 39291186, 2024). "Dysregulation of serum APOL1 and APOM has also been reported in COVID-19 patients." (PMID 36859478, 2023). "We profiled 18 COVID-19–induced cytokines to identify 8 cytokines that were sufficient, in the absence of SARS-CoV-2, to synergistically induce APOL1 expression in primary human glomerular cells and cause podocytopathy in human kidney micro-organoids." (PMID 35472001, 2022). "The glomerular damage in COVID-19 is not common and has been described in patients with APOL1 genotypes, related to collapsing glomerulopathy in black patients." (PMID 35531623, 2022). "Conversely, the lack of APOL1 in the glomeruli of COVID-19–positive but AKI-negative G0G0 autopsy control tissue suggests that COVID-19 infection without APOL1 induction is not a sufficient driver of COVAN disease." (PMID 35472001, 2022). "Given the importance of APOL1 in the pathogenesis of FSGS associated with viral infection and to avoid racial bias, it seems appropriate that APOL1 testing be considered in patients with FSGS associated with COVID-19, regardless of self-reported race." (PMID 37229730, 2023). "We corroborate that in the AA patients with collapsing FSGS, the percentage of patients with COVID-19 and high-risk alleles is more than 90%.1,2,9 On comparison, among the 11 non-AA patients with collapsing FSGS with known APOL1 status, we found three of four (75%) with high-risk variants." (PMID 37229730, 2023). "However, if kidney biopsy is not feasible or possible, APOL1 genotyping of Black or Hispanic individuals infected with COVID-19 and with new or worsening proteinuria and AKI is also likely to be high yield." (PMID 35472001, 2022).
COVID-19 (continued). "Unfortunately, of their 40 patients with COVID-19 with collapsing FSGS, none of them were genotyped for APOL1, and we were not able to include them because of the limited data provided in the abstract." (PMID 37229730, 2023). "On the basis of a case series, we demonstrate that APOL1 protein is abundantly expressed in podocytes and GECs of patients diagnosed with COVAN but not in the glomeruli of healthy control participants or glomeruli of control participants who were COVID-19 positive but COVAN negative." (PMID 35472001, 2022).
sleeping sickness (41 papers, 2010 to 2025). "More than twenty years ago, it was discovered that APOL1 protects humans from infections by trypanosome subspecies that cause African sleeping sickness." (PMID 40643483, 2025). "This genetic signal was later mapped to apolipoprotein L1 (APOL1), where genetic variants are under positive selective pressure for protection against Trypanosoma brucei rhodesiense, a parasite that causes African sleeping sickness." (PMID 39316441, 2024). "gambiense, which cause human African trypanosomiasis, have developed specific mechanisms for avoiding lysis by APOL1, either by binding, avoiding, or degrading the lytic protein." (PMID 38360481, 2024). "Due to the mainly protective association between APOL1 risk alleles and human African trypanosomiasis it has been proposed that trypanosomes are the selective agent for APOL1 G1 and G2 alleles in African populations." (PMID 38360481, 2024). "The relationship between high-risk APOL1 variants and human African trypanosomiasis is well-characterised: G2 is associated with protection from T.b." (PMID 38360481, 2024). "Many African individuals express APOL1 variants that, in heterozygosity, counteract resistance factors from human infective trypanosomes, enabling them to avoid sleeping sickness." (PMID 36880831, 2023). "Circulating APOL1 protein forms part of the trypanolytic complexes that protect humans against infections with the Trypanosoma brucei (T. brucei) that cause African sleeping sickness." (PMID 37969018, 2023). "Carriers of one G1 or G2 polymorphism in APOL1 are protected from African trypanosomiasis, also known as African sleeping sickness." (PMID 36279295, 2022). "In turn, two human APOL1 variants arose in Africa (4000–10,000 years ago), which can kill human-infective trypanosomes and are associated with protection against human African trypanosomiasis in the heterozygous or homozygous genotype." (PMID 34331942, 2021). "APOL1 risk variants G1 and G2 restore the lytic activity of human serum, providing selective advantage to carriers against African sleeping sickness caused by T.b." (PMID 34440683, 2021). "SRA neutralizes APOL1 toxicity following direct coiled‐coiling interaction of its N‐terminal LZ helix with the C‐terminal LZ helix of APOL1, and thus allows the T. rhodesiense parasite to grow in humans, causing sleeping sickness in eastern Africa." (PMID 32530132, 2021). "APOL1 encodes apolipoprotein L1, a trypanolytic serum factor that confers resistance against the parasitic infection that causes African sleeping sickness." (PMID 34722586, 2021). "Two common APOL1 variants, G1 (rs73885319, p.S342G) and G2 (a 6-bp in-frame deletion removing two amino acids, rs71785313, p.N388_Y389del), extend APOL1 restriction to T.b.rhodesiense, the cause of acute human African trypanosomiasis." (PMID 30733721, 2019). "Wild-type APOL1 is primarily considered as the human serum trypanolytic factor, protecting humans against the African trypanosomiasis causative agent Trypanosoma brucei brucei." (PMID 30557319, 2018). "Here, we present a retrospective association study to test the relationship between APOL1 G1 and G2 variants and susceptibility to the two different forms of human African trypanosomiasis, T.b." (PMID 28537557, 2017). "Many studies have confirmed that APOL1 gene mutations (G1 and G2) were associated with African sleeping sickness, atherosclerosis, as well as a variety of kidney diseases." (PMID 28494221, 2017). "ApoL1 has the potential to lyse trypanosome causing African trypanosomiasis known as sleeping sickness." (PMID 27088082, 2016). "In humans, APOL1 is involved in resistance to the parasite that causes sleeping sickness, while IL1F7 and CARD18 play a role in regulating inflammation." (PMID 20698950, 2010).